MUC5AC (mucin 5AC, oligomeric mucus/gel-forming)
Description:
Gel-forming glycoprotein of gastric and respiratory tract epithelia that protects the mucosa from infection and chemical damage by binding to inhaled microorganisms and particles that are subsequently removed by the mucociliary system. Interacts with H.pylori in the gastric epithelium, Barrett's esophagus as well as in gastric metaplasia of the duodenum (GMD).
Synonyms: TBM; MUC5; leB; mucin
Tractability: Small molecule: a structure with a bound ligand is known. Antibody: a drug acting on it is in phase 2 or 3 trials; UniProt places it where antibodies can reach, with high confidence; its Gene Ontology location is reachable by antibodies, with high confidence; UniProt predicts a signal peptide or a membrane-spanning region. Other modalities: a drug acting on it is in phase 2 or 3 trials.
Target class: Secreted protein
Gene: Protein-coding gene on chromosome 11 (1,157,953 to 1,201,138, forward strand). Ensembl gene ENSG00000215182.
Subcellular location: Secreted
Subcellular location (Human Protein Atlas): Vesicles; Predicted to be secreted
Pathways (Reactome):
Disease: Defective C1GALT1C1 causes TNPS; Defective GALNT12 causes CRCS1; Defective GALNT3 causes HFTC
Metabolism of proteins: O-linked glycosylation of mucins; Termination of O-glycan biosynthesis
Immune System: Dectin-2 family
Gene Ontology:
Molecular function: extracellular matrix structural constituent
Cellular component: extracellular exosome; extracellular region; mucus layer; extracellular matrix; Golgi lumen; plasma membrane
Genetic constraint (gnomAD): Loss-of-function variants: 66 observed, 69.37 expected, observed/expected ratio (o/e) 0.95, 90% interval 0.78 to 1.17. The upper end of that interval is the gene's LOEUF score, 1.17, which puts it in group 5 of 6, group 1 being the genes least tolerant of losing a copy. Missense variants: 817 observed, 858.48 expected, observed/expected ratio (o/e) 0.95, 90% interval 0.9 to 1.01. Synonymous variants: 362 observed, 359.84 expected, observed/expected ratio (o/e) 1.01, 90% interval 0.92 to 1.1.
Homologues: Orthologues: chimpanzee MUC5AC (78% identical), mouse Muc5ac (37% identical), rat Muc5ac (37% identical), tropical clawed frog muc5ac (26% identical). Paralogues in human: MUC5B (32% identical), MUC6 (13% identical), MUC19 (13% identical), MUC2 (12% identical), OTOG (11% identical), VWF (11% identical), OTOGL (10% identical), FCGBP (9% identical), TECTA (7% identical), ZAN (7% identical), KCP (6% identical), CRIM1 (4% identical), and 7 more.
Diseases named in the same sentence as MUC5AC in open-access papers:
MUC5AC is named in the same sentence as 268 diseases in open-access papers, as found by Europe PMC text mining. Sharing a sentence is not in itself a finding about the gene and the disease. The quoted sentences say what the papers report.
asthma (213 papers, 2007 to 2026). "Excess production of mucin 5AC (Muc5ac) due to the expansion of goblet cells, alongside airway inflammation and airway remodeling, causes morbidity and mortality in asthma." (PMID 40626045, 2025). "Instead, tethering of MUC5AC to the epithelium has been associated with mucociliary dysfunction and mucus plugging in asthma (61, –, 63)." (PMID 40757824, 2025). "While MUC5B is thought to be more associated with COPD and cystic fibrosis, MUC5AC production is more likely to be relevant to the pathophysiology of asthma." (PMID 39057040, 2024). "Because the tSNPs we uncovered are unlikely to be genotyped in previous GWASs, we assessed the LD of MUC5AC haplogroups with risk and protective alleles for asthma/allergy phenotypes and infection-induced pneumonia/meningitis." (PMID 38991590, 2024). "The primary mucin produced by cup cells is called MUC5AC, and it is strongly linked to the development of numerous respiratory conditions, including bronchiectasis, asthma, and pulmonary cystic fibrosis." (PMID 38542983, 2024). "Interlekin-13 is also known to upregulate MUC5AC, a major airway mucin involved in asthma, making patients with allergic asthma less susceptible to severe COVID-19." (PMID 38961350, 2024). "Variants in MUC5AC have been associated with chronic sputum production, asthma, and pulmonary fibrosis." (PMID 39137525, 2024). "Goblet cells in the bronchiolar epithelium predominantly secretes airway MUC5AC, with goblet cell hyperplasia and the associated mucus hypersecretion contributing to asthma airway remodeling." (PMID 36831258, 2023). "In that study we went on to show that the signal (rs11602802 used as proxy) was associated with mRNA levels of MUC5AC in bronchial epithelial brush samples collected from asthma patients, with the risk allele being associated with elevated MUC5AC." (PMID 37263751, 2023). "In asthma, the expression of MUC5AC increased remarkably by asthma severity; also, it was associated with airway wall thickness." (PMID 37686350, 2023). "The increased expression of MUC5AC is an important marker of airway goblet cell proliferation and mucus hypersecretion in asthma, and it is also an independent risk factor affecting the development and prognosis of asthma." (PMID 38093206, 2023). "Recent data show structural airway changes such as increase in ASM mass and MUC5AC expression in both T2 and non-T2 severe asthma while submucosal glands hyperplasia is associated with T2 intermediate and T2-low asthma." (PMID 37199256, 2023). "In diseases such as chronic obstructive pulmonary disease (COPD) and asthma, MUC5AC is up-regulated, and has been associated with reduced MCT (24, –26)." (PMID 35353667, 2022). "In asthma, goblet cells show an increase in mucin 5AC (MUC5AC), a major component of airway mucus, caused by an increase in Th2 cytokines." (PMID 36555240, 2022). "More specifically, CD4+ T cell responsiveness to allergen exposure correlates well with asthma diagnosis, with associated increases in type 2 cytokines, increased total mucins, and increased MUC5AC in the airways of allergic asthma patients." (PMID 36324676, 2022). "The previously reported moderate-to-severe asthma risk locus near MUC5AC showed modest levels of significance with the same direction of effect (rs11603634, P = 2.99 × 10–3, ORG = 1.11)." (PMID 35368043, 2022). "Muc5AC is known to increase mucus viscoelasticity and is associated with exacerbation risk in severe asthma." (PMID 35997279, 2022). "In asthma models induced by various stimuli, mucus metaplasia is caused by an increase in production and storage of mucins, particularly mucin 5AC (MUC5AC), in airway epithelial cells." (PMID 34822557, 2021). "Increased Muc5ac expression has been associated with airway obstruction, hyper-responsiveness, and severity of asthma." (PMID 34868022, 2021). "Muc5ac is a secretory mucin that has been associated with reduced pulmonary function and asthma exacerbations." (PMID 34868022, 2021).
asthma (continued). "All signals showed associations with the asthma trait including the MUC5AC signal that was identified as a potential moderate-severe asthma signal originally and blood/immune cell trait associations were very prominent." (PMID 35386986, 2021). "More importantly, a positive correlation between EGFR immunoreactivity and MUC5AC mucin staining was noted when bronchial biopsies from healthy volunteers and subjects with mild-to-moderate asthma were compared, suggesting a causal relationship." (PMID 33123005, 2020). "Most recently, a GWAS on asthma severity with large-scale samples (N = 57,695) was reported, and several asthma severity risk genes were identified; such as MUC5AC, KIAA1109, and GATA3." (PMID 33066754, 2020). "This is the first report, to our knowledge, of the MUC5AC locus being specifically associated with increased susceptibility to development of moderate-to-severe asthma in a genome-wide association study." (PMID 30552067, 2019). "The rs11603634 asthma risk allele (G) was correlated with rs11602802 (A) allele, which was associated with increased levels of MUC5AC mRNA." (PMID 30552067, 2019). "Muc5ac has been linked to mucin production and asthma, and shown to be upregulated in OVA challenge mice." (PMID 29086354, 2018). "In an experimental murine model of allergic asthma, increased bronchoalveolar lavage fluid concentrations of SubP were associated with induction of muc5AC mRNA, further suggesting a potential pathogenic role for tachykinins in asthma." (PMID 30081920, 2018). "In Th2‐mediated asthma, goblet cell metaplasia and associated MUC5AC overexpression are mainly attributed to the presence of IL‐13." (PMID 28701525, 2017). "MUC5AC is also a susceptibility gene for moderate-to-severe asthma." (PMID 38453256, 2024). "Our in vivo and in vitro experiments showed that SZYQD and its main active component luteolin play a therapeutic role in relieving asthma symptoms by reducing inflammation and mucus overproduction, which was associated with decreased IL-6 and MUC5AC expression." (PMID 38093206, 2023). "These associations with MUC5AC suggest that the rs12788104 variant may not only play a significant role in development of asthma, but may more generally activate mucus production and chronic cough." (PMID 35347136, 2022). "However, despite overwhelming evidence of a pathogenic role for Muc5ac in asthma, the immunological pathway that controls Muc5ac overexpression remains poorly understood." (PMID 34868022, 2021). "Muc5ac over-expression has been associated with the development of airway mucus plugging, allergic airway hyper-reactivity, and progressive loss of lung function, and asthma exacerbations." (PMID 34868022, 2021). "In addition to known variants already detected in study addressing general asthma previously, three novel loci harboring MUC5AC, GATA3, and KIAA1109 with convincing biological plausibility emerged." (PMID 32060620, 2020). "Using DeepSEA, the moderate-to-severe asthma risk allele (G) at the sentinel SNP rs11603634 near MUC5AC was predicted to result in a log2 fold change of more than 1·5 in function at Forkhead Box A1 (FOXA1) and Forkhead Box A2 (FOXA2) binding sites in airway epithelium." (PMID 30552067, 2019). "This altered ratio of MUC5AC to MUC5B in asthma might be partially explained by the opposite effect of our novel asthma risk allele (G) of rs11603634 on MUC5AC and MUC5B production." (PMID 30552067, 2019). "The association between the asthma risk allele (G) of rs11603634 and increased concentrations of MUC5AC mRNA in bronchial epithelial brush samples, and the predicted effect on FOXA transcription factors provide putative mechanisms because FOXA2 regulates mucin-5AC (MUC5AC) production." (PMID 30552067, 2019). "Given that glandular secretion in response to SubP is defective in CF, a speculation is that SubP-mediated secretion in CF might be associated with enhanced muc5AC to muc5B secretion ratios, effectively mimicking asthma." (PMID 30081920, 2018).
asthma (continued). "Similarly, examining how acute and/or repeated applications of neuropeptides affect expression of mucins (e.g., muc5AC, muc5B) in asthma, COPD, and CF would reveal a potentially causative role for neuropeptides in airway mucus phenotypes." (PMID 30081920, 2018). "Additionally, lung MUC5AC overexpression has been reported in cases of fatal asthma and is thus associated with adverse outcomes." (PMID 29884817, 2018). "Variants in the 11p15 MUC5B and MUC5AC locus have been associated with AHR in asthma." (PMID 29186064, 2017). "Goblet cell gene expression analysis revealed that HDM exposure induced multiple asthma‐associated transcripts, including chloride channel calcium‐activated 1 (Clca1/Gob‐5), mucin 5, subtypes A and C, tracheobronchial/gastric (Muc5ac), intelectin 1 (Itln1), and intelectin 2 (Itln2/B)." (PMID 27621809, 2016). "However, we have previously shown that a proxy of rs779167905 (rs11602802, r2=0.94) was associated with mRNA levels of MUC5AC in bronchial epithelial brush samples collected from asthma patients, with the risk allele being associated with elevated MUC5AC expression." (PMID 37263751, 2023). "Furthermore, genetic studies have provided evidence that genetic variations in the Muc5ac region of chromosome 11 were associated with asthma and contribute to Muc5ac expression that may underlie propensity to mucus plugging during asthma exacerbations." (PMID 34868022, 2021). "For example, adeno-associated virus serotype 6 (AAV6) has been successfully used as a viral gene vector to transduce airway epithelial cells and reduce mucin 5AC (MUC5AC) expression for the treatment of asthma." (PMID 41596367, 2026). "In contrast, airway sections from patients with severe asthma demonstrated significantly increased epithelial thickness, increased numbers of MUC5AC+ GC, and occasional luminal occlusion by a mucous plug in the small airways (<2 mm in diameter)." (PMID 40446022, 2025). "As anticipated, we observed increased MUC5AC and MUC5B mucin peptides associated with EVs isolated from COPD and asthma BW specimens." (PMID 40553562, 2025). "Asthma mucus plugs were tethered to airways showing infiltration with innate lymphoid type 2 cells and hyperplasia of smooth muscle cells and MUC5AC-expressing goblet cells." (PMID 40091838, 2025). "Consistent with the findings in other asthma studies, H2 inhalations were found to mitigate histopathological changes, mucus hypersecretion, and excessive mucin 5AC (MUC5AC) expression." (PMID 40362357, 2025). "Airway mucus hypersecretion leads to a higher number of goblet cells in the airway epithelium, and this, in turn, leads to elevated MUC5AC expression, exacerbating asthma." (PMID 40709340, 2025). "Taken together, findings from the asthma and COPD literature converge on a model in which MUC5AC is more closely linked to disease pathology, whereas MUC5B plays a comparatively lesser role." (PMID 41561092, 2025). "The airway epithelium of mucus-plugged airways in asthma is characterized by hyperplasia of basal cells and MUC5AC-positive goblet cells." (PMID 40091838, 2025). "The relatively acellular and MUC5AC-rich profile of mucus plugs in fatal asthma is consistent with their formation because of acute degranulation of MUC5AC-positive goblet cells." (PMID 40091838, 2025). "In murine asthma models, Muc5ac deletion reduces allergen-induced mucus plugging and airway hyperresponsiveness, indicating that MUC5AC is required for these pathological features, whereas Muc5b deficiency does not confer comparable protection." (PMID 41561092, 2025). "Muc5ac is a gel-forming mucin that is elevated in patients with lung diseases, such as asthma, chronic obstructive pulmonary disease, and cystic fibrosis." (PMID 40509336, 2025). "Whole-transcriptome sequencing identified key inflammatory genes, such as IL1B, CCL17, and MUC5AC, that were upregulated in asthma patients, while immune regulatory factors like FOXP3 and IFNG were higher in healthy controls." (PMID 40309741, 2025).
asthma (continued). "MUC5AC is important in mucus hyperproduction in asthma, with approximately 20 mucin genes involved in mucus secretion." (PMID 40709340, 2025). "The MUC5AC-expressing goblet cells were also larger in the mucus-plugged asthma airways, indicating that MUC5AC-expressing goblet cells undergo both hyperplasia and hypertrophy." (PMID 40091838, 2025). "MUC5AC-rich mucus plugs in asthma are tethered to an epithelium that is buckled to form mucosal folds." (PMID 40091838, 2025). "For instance, decreasing the expression of miR-145 increased the expression of epidermal growth factor receptor (EGFR), which regulates mucin 5AC (MUC5AC), and its overexpression in asthma was linked to pathological mucus hypersecretion." (PMID 41156032, 2025). "Because MUC5AC oversecretion exacerbates asthma symptoms, effective asthma therapies should target the reduction of MUC5AC production and secretion." (PMID 40869396, 2025). "There was a significant positive correlation between sputum MUC5AC levels and the proportion of eosinophils in steroid-untreated patients with mild asthma." (PMID 40529570, 2025). "In airway sections from individuals with severe asthma, we found an increased airway epithelial thickness and mucous cell metaplasia marked by significant increases in MUC5AC staining of GC." (PMID 40446022, 2025). "In fact, S221R (rs35783651) is a tagging SNP for H3 variants and is an expression quantitative trait locus (eQTL) for decreased expression of MUC5AC in pediatric asthma." (PMID 40035770, 2025). "In asthma, substance P produced by airway sensory neurons amplifies allergy-induced GC hyperplasia and MUC5AC hypersecretion." (PMID 39958344, 2025). "In COPD and asthma samples, we found an increased number of MUC5AC-positive cells (goblet cell metaplasia), consistent with elevated exposure to IL-13." (PMID 39255033, 2024). "MUC5AC, gel-forming mucin and a member of the secreted glycoprotein family, is thought to contribute to the airway hyperresponsiveness in asthma patients." (PMID 38395974, 2024). "ER stress induced by IL‐13 increases MUC5AC expression in airway epithelial cells, and an inhibitor of ER stress partially attenuates MUC5AC expression in asthma." (PMID 39365189, 2024). "Its overexpression resulted in pulmonary inflammation and elevated levels of MUC5AC in mice with asthma." (PMID 39361370, 2024). "Mucus hypersecretion can also occur in non-T2 asthma, and mouse studies have shown that neutrophilic inflammation is associated with increased expression of CLCA1, MUC4, MUC5AC and MUC5B." (PMID 38453256, 2024). "Specifically, MUC5AC is upregulated in people with asthma, particularly in those with the eosinophilic T2 endotype." (PMID 38453256, 2024). "The risk alleles for three SNPs associated with asthma/allergy (rs35225972,39 rs11245962,40 and rs2841584541; EUR cohorts) are in moderate LD with H1 variants of MUC5AC." (PMID 38991590, 2024). "Abnormalities in these cells lead to impaired airway mucus clearance in asthma, particularly owing to ciliated cell damage and MUC5AC+ mucus plug formation." (PMID 39391497, 2024). "By comparing the enriched signaling pathways in mild asthma and healthy controls, we identified “IL-17 signaling pathway” as the only important signaling pathway in which MUC5AC, MUC5B and CXCL8 showed significant enrichment." (PMID 38351296, 2024). "MUC5AC was previously correlated with asthma, since it is induced by the Th2 immune response triggered by allergic eosinophilic asthma." (PMID 38542471, 2024). "While the increase in MUC5AC expression in asthma is consistent, results concerning MUC5B are more conflicting." (PMID 38339210, 2024). "Then, we assessed the levels of IgE, Th2 cytokines (IL-4, IL-5, and IL-13), eotaxin, TGF-β1, and MUC5AC using ELISA kits to detect the effect of scutellarin on the release of asthma-related cytokines in ovalbumin-challenged mice." (PMID 38168709, 2024).